PDGFRA (platelet derived growth factor receptor alpha)
Diseases named in the same sentence as PDGFRA in open-access papers (continued):
Sharing a sentence is not in itself a finding about the gene and the disease.
glioma (continued). "The restriction of this regulatory interaction to proneural gliomas is perhaps not surprising given the highly distinctive molecular profiles exhibited by different GBM expression subclasses, and the central role of PDGFRA in proneural gliomagenesis." (PMID 22479456, 2012). "The tumor at this stage was not easily distinguishable from nontumor tissues without YFP immunohistochemistry, yet both PDGFRα, an oligodendrocyte precursor cell (OPC) marker, and GFAP, an astrocyte marker, were ectopically expressed on the tumor side, indicating that the tumor is a glioma." (PMID 32573857, 2020).
glioblastoma (207 papers, 2005 to 2026). The most malignant astrocytic tumor (WHO grade IV). "Epidermal growth factor receptor (EGFR) is the most frequently mutated receptor in glioblastoma (57% of cases), followed by platelet-derived growth factor receptor (PDGFRA) (13%), fibroblast growth factor receptor (FGFR) (3.2%), and c-MET (1.6%)." (PMID 40332381, 2025). "PDGFRA mutations are common in glioblastoma; one study found that 40% of glioblastomas had PDGFRA mutations." (PMID 40564017, 2025). "Researchers demonstrated that the expression of PDGFRA is associated with drug efficacy in treating glioblastoma." (PMID 40564017, 2025). "NF1 mutations are primarily associated with the mesenchymal glioblastoma subtype, and PDGFRA is correlated with the proneural glioma subtype." (PMID 40564017, 2025). "This study describes a novel, pathogenic MDM2(exon 1)::PDGFRA(exon 8) fusion detected after cetuximab treatment in an EGFR-amplified glioblastoma." (PMID 40819143, 2025). "PDGFRA-amplified or mutated adult-type IDH-wild-type glioblastomas show significantly higher frequencies of corpus callosum involvement and multifocal lesions." (PMID 40853542, 2025). "PDGFRA amplifications and mutations are common in glioblastoma but appear to be somewhat mutually exclusive with IDH mutant tumors, which nonetheless highly express PDGFRA." (PMID 37415185, 2023). "The Cancer Genome Atlas(TCGA) data show that PDGFRA mutations and amplifications are also common in malignant tumors, such as glioblastoma, melanoma, non-small cell lung cancer, and hematologic malignancies." (PMID 37454137, 2023). "Platelet-derived growth factor receptor alpha (PDGFRA) is the second most frequently mutated tyrosine kinase receptor in glioblastoma (GBM)." (PMID 35911637, 2022). "EGFR is the most frequently altered receptor tyrosine kinase (RTK) in glioblastoma, but amplification and activating mutation or fusions have been also reported in other RTKs, such as PDGFRA, MET, FGFR, and NTRK1." (PMID 34572759, 2021). "In the mouse experiment, the ATM gene was involved in the suppression of glioblastoma by the down-regulation of glioblastoma-associated genes such as the PDGFRA gene." (PMID 33353229, 2020). "In a scRNA-seq glioblastoma dataset, we discover a recurrent cell-level mutation in the PDGFRA gene that is highly correlated with a well-known in-frame deletion in the gene." (PMID 31028395, 2019). "In the glioblastoma dataset (iii), we discover a cell-level mutation that is highly correlated with a well-known 24 bp in-frame deletion in the PDGFRA gene." (PMID 31028395, 2019). "One of the glioblastoma subtypes, proneural subtype, has features of high expression of platelet derived growth factor receptor alpha (PDGFRA) or isocitrate dehydrogenase 1 (IDH1) gene mutation." (PMID 30709063, 2019). "PDGFRA mutations in glioblastoma, treated with regorafenib, sunitinib malate or pazopanib hydrochloride." (PMID 29507702, 2018). "The selected PDGFRA mutations were mainly from cutaneous melanoma (7 mutations), glioblastoma (6 mutations), and colon/ colorectal adenocarcinoma (5 mutations)." (PMID 30389923, 2018). "Subset analysis demonstrated that positive PDGFRA expression was associated with poor outcome within the K27M mutated glioblastoma subgroup (p = 0.03)." (PMID 26452024, 2016). "The association of PDGFRA expression with poor prognosis in K27M mutated glioblastomas in our study was in line with previous observation." (PMID 26452024, 2016). "The mutation found in 40% of glioblastomas with amplified PDGFRA consists of a deletion of exons 8 and 9 coding for an extracellular domain fragment." (PMID 24709958, 2014). "c-KIT, VEGFR2 and PDGFRα have previously been found to be amplified in 15–33% of primary glioblastomas and amplification of c-KIT and PDGFRα to be associated with poor survival of glioblastoma patients." (PMID 25025175, 2014).
glioblastoma (continued). "Activating PDGFRα mutations have been found in a small percentage of glioblastomas and gastrointenstinal stromal tumors (GIST)." (PMID 24709958, 2014). "Within glioblastoma specimens, PDGFRA amplification alone was linked to oligodendroglial, small cell and sarcomatous tumour cell morphologies, and rare MGMT promoter methylation." (PMID 23990986, 2013). "EGFR, NF1, and PDGFRA mutations are more frequent in glioblastoma." (PMID 40564017, 2025). "Analysis of a glioblastoma cohort indicates PDGFRA structural variants often co-occur with amplification and may serve as biomarkers." (PMID 40819143, 2025). "Using the TTD database, we discovered that EGFR, ABAT, and PDGFRA are strongly associated with AQP4 expression in the glioblastoma (GBM) classification, and these factors could be the potential AQP4-related immunotherapy targets." (PMID 36523816, 2022). "In glioblastoma tumors, the amplification, mutation and rearrangement of the PDGFRα gene are seen." (PMID 34199460, 2021). "A significant research analysis in glioblastoma of approximately 198 patients has shown the prevalence of amplification-linked extrachromosomal mutations due to which there are momentous mutations in oncogenes such as PDGFRA or EGFR in glioblastoma due to environmental effects." (PMID 31285839, 2019). "Interestingly, tumors with positive PDGFRA immunohistochemical expression exhibited poorer prognosis and identified an aggressive subset of tumors among K27M mutated glioblastomas." (PMID 26452024, 2016). "Moreover, similar to EGFRvIII mutants, deletions in the extracellular domain of PDGFRA have been already reported in as many as 40% of glioblastomas with PDGFRA amplification and were associated with increased tyrosine-kinase activity." (PMID 22389665, 2012). "To further examine this variant, we aimed to generate human glioblastoma multiforme (GBM) cells harboring this variant, as PDGFRA is one of the most crucial driver genes in GBM." (PMID 36613947, 2022). "We performed comparative studies to determine the optimal editing conditions for the introduction of platelet-derived growth factor receptor alpha (PDGFRA) variants in human glioblastoma multiforme (GBM) cell lines." (PMID 36613947, 2022). "PDGFRA encodes receptor tyrosine kinase, which plays a role in glioblastoma initiation and progression and is also known as an indicator of GBM pro-neural subtype." (PMID 36231068, 2022). "Interestingly, the DEG from the high grade phenotype share a common genetic signature with a proneural type of glioblastoma (Gene set: VERHAAK_GLIOBLASTOMA_PRONEURAL), which is distinguished from other glioblastomas by lower age, better prognosis, PDGFRA expression, and frequent IDH1 mutation." (PMID 26524630, 2015). "These preclinical findings underscore the importance of context-dependent therapeutic strategies for PDGFRA-altered glioblastomas." (PMID 40819143, 2025). "Knockdown or knockout of PDGFRA in gastrointestinal (GI) and glioblastoma (GBM) cancer cells suppressed tumour proliferation." (PMID 39780187, 2025). "The findings support the notion that PDGFRA fusions are frequently developed during the emergence of PDGFRA amplifications in glioblastoma." (PMID 40819143, 2025).
glioblastoma (continued). "While PDGFRA and EGFR amplifications typically demonstrate homogeneous intratumoral distribution, EGFRvIII mutations in glioblastomas exhibit marked spatial and temporal intratumoral heterogeneity." (PMID 40853542, 2025). "Although our study focused on NF1 loss leading to Ras activation, RTKs, such as PDGFRA and EGFR, which are recurrently mutated in glioblastoma, can also activate Ras signaling through Ras GEFs such as SOS1." (PMID 40985888, 2025). "Future in vivo studies are necessary to evaluate the pharmacokinetics, blood-brain barrier permeability, and comparative therapeutic efficacy of type I and type II PDGFRA TKI inhibitors in glioblastoma models with PDGFRA alterations." (PMID 40819143, 2025). "Platelet-derived growth factor receptor alpha (PDGFRA) is a crucial driver gene in glioblastoma (GBM)." (PMID 39996812, 2025). "In Glioblastoma, analysis of PDGFRA protein and downstream mediators have revealed that Valtrate effectively inhibits PDGFRA/MEK/ERK signaling pathways." (PMID 40894227, 2025). "The growth of glioblastomas of the proneuronal subtype depends on PDGFRA, so another growth factor, PDGF, is used for their cultivation." (PMID 38392188, 2024). "In our sample, amplification or mutation of the EGFR gene, as well as amplification of the PDGFRA and KIT genes, potentially leading to their overexpression, were prevalent in HGG IDH—wildtype glioblastoma." (PMID 39684714, 2024). "Inhibition of PDGFRA has demonstrated reduced tumor growth and improved survival in preclinical glioblastoma models." (PMID 39606019, 2024). "Two patients with MET amplified and PDGFRA/KDR amplified glioblastoma were treated with cabozantinib and attained partial response." (PMID 38143440, 2023). "For instance, Platelet-Derived Growth Factor Receptor Alpha (PDGFRA) expression trends show differences in overall survival among glioblastoma patients." (PMID 37894355, 2023). "The PDGFRA gene plays an important role in the embryonic development as well as the pathogenesis of various haematopoietic malignancies and glioblastomas." (PMID 37184764, 2023). "Expression of PDGFRA, a glioblastoma (GBM)‐associated gene, was observed to be lower in comparisons of both CIC‐KO to CIC‐WT cells and IDH1‐R132H to IDH1‐WT cells, indicating that both CIC loss and the expression of IDH1‐R132H independently resulted in reduced expression of PDGFRA." (PMID 34767259, 2022). "The CNV of PDGFRA was positively correlated with its mRNA levels in glioblastoma multiforme (GBM) (r = 0.43)." (PMID 36032075, 2022). "EGFR amplification is common in adult IDH-WT glioblastoma, while PDGFRA activation is more common in pediatric tumors, including H3K27M-mutant diffuse midline gliomas." (PMID 35973991, 2022). "It has been shown that CN gain at the PDGFRA locus can influence the relative frequency of tumor malignant cells and promote the tumor growth, whereas high expression of PDGFRA in glioblastoma can markedly improve the prognosis of patients." (PMID 35212838, 2022). "In general, TERT overexpression was the main mechanism of telomere elongation in IDH wild-type glioblastoma, except for the PDGFRA subgroup." (PMID 34572759, 2021).
glioblastoma (continued). "With regard to previous observations of an active PDGFRA signaling loop in glioblastoma we here experimentally show this can be maintained by SOX2, and subsequently turned off by SFRP2, potentially acting via KLF4." (PMID 34021259, 2021). "PDGFRα signaling is activated by HCMV glycoprotein B in glioblastomas, promoting survival and motility of glioma cells." (PMID 34575976, 2021). "Knockdown of GRB14 (γ) or PDGFRα (δ) attenuated proliferation, radioresistance, apoptosis radioresistance, invasion, and migration abilities of glioblastoma cell lines previously treated with ldrEXOs." (PMID 33867829, 2021). "Up-regulation of PDGFRα (ε) rescued progression and radioresistance of glioblastoma cell lines previously treated with knockdown of GRB14." (PMID 33867829, 2021). "This is surprising because activation of PDGFRα by glycoprotein B in glioblastomas increases cancer progression and metastases." (PMID 34575976, 2021). "Up-regulating PDGFRα can recover the tumor-promoting function of ldrEXOs in glioblastoma cell lines previously treated with inhibition of GRB14." (PMID 33867829, 2021). "The association of the genetic alterations in signaling pathway component genes such as PDGFRα, EGFR and NF1 was explored in IDHwt glioblastomas, with each mutation being shown to favor a particular state." (PMID 34948008, 2021). "DNM2 mediates the Platelet Derived Growth Factor Receptor α (PDGFRα)-stimulated growth and invasion of glioblastoma cells through the formation of a Src-phosphorylated DNM2-PDGFRα-tyrosine-protein phosphatase non-receptor type 11 (SHP2) complex." (PMID 34294140, 2021). "We identified the role of low-dose radiation-induced exosomal circ-METRN and miR-4709-3p/GRB14/PDGFRα pathway, bringing a novel insight into the investigation of exosomal circRNAs and providing potential targets for anti-glioblastoma therapy." (PMID 33867829, 2021). "The mechanism of low-dose radiation-induced exosomal circ-METRN via miR-4709-3p/GRB14/PDGFRα pathway in glioblastoma cells was elucidated by using the schematic cartoon." (PMID 33867829, 2021). "This population included expected hits such as PDGFRα, which has previously been shown to be necessary for glioblastoma invasion, suggesting our assay was capable of identifying known regulators of migration." (PMID 31570734, 2019). "Fifteen percent of patients with glioblastomas carried PDGFRA amplification, which was also found in soft tissue malignancy." (PMID 31138756, 2019). "Mutations in the PDGFRα gene have been found in 5% of gastrointestinal stromal cancer (GIST) and amplifications of PDGFRα were reported in 5–10% of glioblastoma multiforme, in oligodendrocytoma, esophageal squamous cell carcinoma and artery intimal sarcomas." (PMID 29455662, 2018). "The cause of PDGFRA deregulation in ENKTL remains uncertain and is not a result of genomic imbalances, gene mutations or overrepresentation of the H2α haplotype, the latter is known to result in up-regulation of PDGFRA in glioblastoma." (PMID 29966370, 2018). "We examined the cell-to-cell distribution of EGFR and PDGFRA protein expression in glioblastoma derived lines of different genotypes by dual FACS." (PMID 28831081, 2017). "CRISPR/Cas9‐mediated deletion (4–13 bp) of the insulator CTCF binding site in the PDGFRA locus induced the expression of PDGFRA by 1.6‐fold in human glioblastoma cells." (PMID 28255028, 2017). "In brain cancer, dynamin 2 is a downstream effector of the PDGFRα-PI3K/SHP-2 signalling in glioma cells and mediates PDGFRα -SHP-2-promoted glioblastoma growth and invasion." (PMID 28402939, 2017). "Comparing PDGFRA expression across BRAF, IDH1 and H3F3A mutated glioblastomas, positive expression co-occurred in 50% (10/10) of H3F3A mutated tumors, 27.8% (5/13) of IDH1 mutated tumors and 12.5% (2/16) of BRAF mutated tumors (p = 0.05)." (PMID 26452024, 2016).